SGO1 (shugoshin 1)
Description:
Plays a central role in chromosome cohesion during mitosis by preventing premature dissociation of cohesin complex from centromeres after prophase, when most of cohesin complex dissociates from chromosomes arms. May act by preventing phosphorylation of the STAG2 subunit of cohesin complex at the centromere, ensuring cohesin persistence at centromere until cohesin cleavage by ESPL1/separase at anaphase. Essential for proper chromosome segregation during mitosis and this function requires interaction with PPP2R1A. Its phosphorylated form is necessary for chromosome congression and for the proper attachment of spindle microtubule to the kinetochore. Necessary for kinetochore localization of PLK1 and CENPF. May play a role in the tension sensing mechanism of the spindle-assembly checkpoint by regulating PLK1 kinetochore affinity. Isoform 3 plays a role in maintaining centriole cohesion involved in controlling spindle pole integrity. Involved in centromeric enrichment of AUKRB in prometaphase.
Synonyms: SGOL1; NY-BR-85; CAID; SGO
Tractability: PROTAC: UniProt records ubiquitination sites on it; ubiquitination databases record sites on it.
Gene: Protein-coding gene on chromosome 3 (20,160,593 to 20,186,782, reverse strand). Ensembl gene ENSG00000129810.
Subcellular location: Nucleus; Chromosome, centromere; Chromosome, centromere, kinetochore; Cytoplasm, cytoskeleton, spindle pole; Cytoplasm, cytoskeleton, microtubule organizing center, centrosome; Nucleus speckle
Subcellular location (Human Protein Atlas): Nucleoplasm; Cytosol; Kinetochore
Pathways (Reactome):
Cell Cycle: Amplification of signal from unattached kinetochores via a MAD2 inhibitory signal; Cyclin A/B1/B2 associated events during G2/M transition; EML4 and NUDC in mitotic spindle formation; Mitotic Prometaphase; Resolution of Sister Chromatid Cohesion; Separation of Sister Chromatids
Signal Transduction: RHO GTPases Activate Formins
Gene Ontology:
Molecular function: kinase binding; protein binding
Biological process: attachment of spindle microtubules to kinetochore; centriole-centriole cohesion; chromosome segregation; meiotic chromosome segregation; mitotic sister chromatid cohesion, centromeric; homologous chromosome segregation; meiotic sister chromatid cohesion
Cellular component: centrosome; chromosome, centromeric region; condensed chromosome, centromeric region; kinetochore; nuclear speck; nucleoplasm; spindle pole; cytosol; mitotic cohesin complex; nucleus
Genetic constraint (gnomAD): Loss-of-function variants: 33 observed, 42.6 expected, observed/expected ratio (o/e) 0.77, 90% interval 0.59 to 1.04. The upper end of that interval is the gene's LOEUF score, 1.04, which puts it in group 4 of 6, group 1 being the genes least tolerant of losing a copy. Missense variants: 573 observed, 563.34 expected, observed/expected ratio (o/e) 1.02, 90% interval 0.95 to 1.09. Synonymous variants: 177 observed, 196.51 expected, observed/expected ratio (o/e) 0.9, 90% interval 0.8 to 1.02.
Homologues: Orthologues: chimpanzee SGO1 (98% identical), macaque SGO1 (94% identical), pig SGO1 (75% identical), rabbit SGO1 (74% identical), dog SGO1 (73% identical), guinea pig SGO1 (71% identical), rat Sgo1 (54% identical), mouse Sgo1 (53% identical), tropical clawed frog sgo1 (32% identical), zebrafish sgo1 (25% identical). Paralogues in human: SGO2 (18% identical).
Diseases named in the same sentence as SGO1 in open-access papers:
SGO1 is named in the same sentence as 65 diseases in open-access papers, as found by Europe PMC text mining. Sharing a sentence is not in itself a finding about the gene and the disease. The quoted sentences say what the papers report.
chronic atrial and intestinal dysrhythmia (15 papers, 2015 to 2025). A syndrome characterized by a unique combination of cardiac arrhythmias and intestinal pseudo-obstruction. "WES revealed the presence of a homozygous missense variant in the SGO1 gene (p.Lys23Glu), a known pathogenic founder mutation associated with autosomal recessive chronic atrial and intestinal dysrhythmia (CAID syndrome, MIM: 616201)." (PMID 35606766, 2022). "The mutation (K23E) in CAID-syndrome patients is located in the N-terminal of SGO1 (residues 1-115), which is a highly conserved coiled-coil domain that confers interaction with other cohesin-associated proteins, such as PP2A5,23." (PMID 33953173, 2021). "Indeed, the CAID syndrome is caused by a homozygous SGO1 mutation (K23E), which encodes for the Shugoshin-1 protein that protects sister chromatid cohesion mainly to ensure chromosomal stability during mitosis and meiosis." (PMID 40890826, 2025). "A mutation in Shugoshin-1 causes the Chronic Atrial and Intestinal Dysrhythmia (CAID) Syndrome, but the underlying mechanisms are unknown." (PMID 33953173, 2021). "Third, a substitution in the N-terminal domain of Sgo1 (K23E) disrupts its ability to directly interact with the pacemaker ion channel HCN4 in the membrane of cardiomyocytes of patients with Chronic Atrial and Intestinal Dysrhythmia Syndrome (CAID)." (PMID 38152060, 2023). "SGO1 mutation (p.Lys23Glu) was identified retrospectively in four patients as the CAID syndrome had not yet been discovered when these patients were initially diagnosed with PIPO." (PMID 41245052, 2025). "The authors defined this condition as chronic atrial and intestinal dysrhythmia (CAID) syndrome, i.e., a novel generalized dysrhythmia, indicative of the role of SGO1 in mediating the integrity of human cardiac and gut rhythms, the latter being generated by ICC." (PMID 36551277, 2022). "The clinical p.Lys23Glu mutation leads to an impairment in the interaction between Shugoshin-1 and HCN4, along with depressed funny-current and dysrhythmic activity in induced pluripotent stem cell derived cardiomyocytes derived from Chronic Atrial and Intestinal Dysrhythmia Syndrome patients." (PMID 33953173, 2021). "Here, we show that disordered cardiac pacemaker function in CAID syndrome is attributable to disruption by the SGO1-K23E mutation of an SGO1 non-canonical function to enhance the cardiac pacemaker funny current (If)." (PMID 33953173, 2021). "The mutation p.Lys23Glu in the cohesin protein Shugoshin-1 causes severe heart arrhythmias due to sinoatrial node dysfunction and a debilitating gastrointestinal motility disorder, collectively termed the Chronic Atrial and Intestinal Dysrhythmia Syndrome, linking Shugoshin-1 and pacemaker activity." (PMID 33953173, 2021). "Here, we study the mechanism by which Shugoshin-1 affects cardiac pacing activity with two cell models: neonatal rat ventricular myocytes and Chronic Atrial and Intestinal Dysrhythmia Syndrome patient-specific human induced pluripotent stem cell derived cardiomyocytes." (PMID 33953173, 2021). "Here, the authors show that Shugoshin-1 controls cardiac pacemaker activity by interacting with HCN4 to enhance its cell-surface expression, and that the CAID-Syndrome mutation disrupts cardiac pacemaking by interfering with this important non-canonical interaction." (PMID 33953173, 2021). "Our results confirmed that the non-canonical interaction between HCN4 and SGO1 is likely responsible for pacemaker dysfunction in CAID Syndrome." (PMID 33953173, 2021). "Further work is needed to clarify whether SGO1 interacts with intestinal HCN channels and, if so, whether disruption of this interaction might contribute to the intestinal pseudo-obstruction component of CAID syndrome." (PMID 33953173, 2021).
chronic atrial and intestinal dysrhythmia (continued). "Our work reveals a critical non-canonical, cohesin-independent role for Shugoshin-1 in maintaining cardiac automaticity and identifies potential therapeutic avenues for cardiac pacemaking disorders, in particular Chronic Atrial and Intestinal Dysrhythmia Syndrome." (PMID 33953173, 2021).
hepatocellular carcinoma (8 papers, 2015 to 2025). A malignant tumor that arises from hepatocytes. "Gene silencing using the CRISPR/Cas9sgRNA system has revealed that loss of Shugoshin 1 (SGOL1), that plays a crucial role in cell mitosis, may cause resistance to sorafenib in hepatocellular carcinoma." (PMID 39696697, 2024). "The depletion of Sgo1 reduced cell viability of hepatoma cell lines including HuH7, HepG2, Hep3B, and HepaRG." (PMID 25638162, 2015). "Together, these results highlight the crucial role of Sgo1 in the maintenance of cell viability and a proper mitotic progression in transformed hepatoma cells." (PMID 25638162, 2015). "Our results indicated that, in comparison to immortalized cells, transformed hepatoma cells were more sensitized to spindle assembly checkpoint (SAC)-dependent mitotic cell death induced upon Sgo1 depletion." (PMID 25638162, 2015). "The most intriguing finding in the present study is the distinct sensitivity to Sgo1 depletion among hepatoma cell lines and immortalized cells." (PMID 25638162, 2015). "Together, these results supported the upregulation of Sgo1 protein expression in hepatocellular carcinoma." (PMID 25638162, 2015). "Together, these results highlight the essential role of Sgo1 in the maintenance of a proper mitotic progression in hepatoma cells and suggest that Sgo1 is a promising oncotarget for HCC." (PMID 25638162, 2015). "This suggests that hepatoma cells generally require a high level of Sgo1 to support proper mitotic progression and cell proliferation." (PMID 25638162, 2015). "Sgo1 mRNA was barely detected in the majority of normal tissues but was significantly expressed in various transformed hepatoma cell lines." (PMID 25638162, 2015). "To explore whether Sgo1 is also involved in sister chromatid cohesion in hepatoma cells, we examined wwprecocious sister chromatid separation upon the depletion of Sgo1 in HuH-7 cells." (PMID 25638162, 2015). "With regard to the relatively high expression level of Sgo1 observed in HCC and hepatoma cell lines, we suggest that hepatoma cells may demand a high level of Sgo1 for the maintenance of sister chromatid cohesion." (PMID 25638162, 2015). "Notably, among the six hepatocyte-derived cell lines, hepatoma cell lines expressed 3-10-fold higher levels of Sgo1 when compared with immortalized NeHepLxHT cells." (PMID 25638162, 2015). "Thus, mitotic cell death induced upon Sgo1 depletion in hepatoma cells is mediated by persistent activation of the spindle assembly checkpoint." (PMID 25638162, 2015). "Our findings indicate that Sgo1 is a common survival factor for hepatoma cells." (PMID 25638162, 2015). "In addition, we explored the essential roles of Sgo1 in the maintenance of cell survival on transformed HeLa cells and four different hepatoma cell lines, as well as two immortalized cell lines." (PMID 25638162, 2015). "We found that the expression of Sgo1 mRNA was relatively low in normal tissues, but was upregulated in 82% of hepatocellular carcinoma (HCC), and correlated with elevated alpha-fetoprotein and early disease onset of HCC." (PMID 25638162, 2015). "Shugoshin 1 (SGO1, otherwise called Shugoshin-Like 1; SGOL1), a member of the shugoshin (SGO) family of proteins, has been proven to play an important role in maintaining a proper mitotic progression in hepatoma cells." (PMID 34200261, 2021). "Using time-lapse microscopy, we showed that hepatoma cells were delayed and ultimately die in mitosis in the absence of Sgo1." (PMID 25638162, 2015). "It is not clear why hepatoma cells are more sensitive to Sgo1 depletion than immortalized cells." (PMID 25638162, 2015).
breast carcinoma (7 papers, 2014 to 2025). "Furthermore, we conducted in vitro and in vivo experiments in breast cancer cell line and lung cancer cell line to validate the association between tumor proliferation and metastasis and SGO1 expression." (PMID 40861810, 2025). "Our group pioneered the study of SGO1 in breast cancer in general by demonstrating, using cBIOPORTAL, that the overexpression of SGO1 in breast tumors correlates with the overexpression of the E2F transcriptional activators E2F1, E2F2, and E2F3." (PMID 37122033, 2023). "To test our hypothesis, we first examined SGO1 protein expression levels in breast cancer cell line MDA-MB-231 and lung cancer cell line A549." (PMID 40861810, 2025). "The supression of SGO1 activity in TNBC harboring dysregulated expression of SGO1 may be a potential target for preventing breast cancer growth and metastasis." (PMID 37122033, 2023). "Functional assays in breast cancer cell line MDA-MB-231 and lung cancer cell line A549 showed SGO1 knockdown inhibited proliferation, migration, and invasion, with xenograft models confirming reduced tumor growth." (PMID 40861810, 2025). "Our laboratory has demonstrated that deregulation of regulators of the centrosome cycle, mitosis, and G1/S phase including Cdk4, the E2F activators (E2F1, E2F3a), Nek2, Sgo1, and Mps1/TTK are required to maintain high CA and CIN in Her2+ breast cancer cells." (PMID 29100415, 2017). "Specifically, breast cancer cells overexpressed GINS2, TTK, CEP192, and shugoshin 1 and have lower levels of C-Nap1, semaphorin 6A, MDM2 and SFRP1." (PMID 25278993, 2014). "To address whether our observations in mammary epithelial cells are translated into breast cancers, we performed TCGA analysis on selected SAC proteins, including BubR1, NDC80, Sgo1, and Mps1/TTK in relation to E2Fs genes using cBioPortal." (PMID 29100415, 2017).
colorectal cancer (7 papers, 2014 to 2025). A primary or metastatic malignant neoplasm that affects the colon or rectum. "For example, SGO1 expression is decreased in colorectal cancer and SGO1 downregulation causes G2/M arrest, apoptosis, and chromosome instability leading to tumorigenesis." (PMID 37122033, 2023). "On the other hand, downregulation of Sgo1 has been linked to chromosome instability in colorectal cancer." (PMID 25638162, 2015). "On the other hand, Sgo1 expression is decreased in colorectal cancer, and the depletion of Sgo1 caused G2/M arrest, apoptosis, and chromosome instability in a colon cancer cell line." (PMID 25638162, 2015). "Mice heterozygous for SGO-1 showed increased chromosome instability and susceptibility to tumors, and mutations in human SGO-1 have been associated with gastric and colorectal cancers, as well as altered heart and gut rhythm." (PMID 32547963, 2020).
lung carcinoma (6 papers, 2015 to 2025). "We further explored the diagnostic significance of SGO1 in lung cancer, and ROC curve analysis was performed." (PMID 35592680, 2022). "Meanwhile, the expression of SGO1 in lung cancer and triple-negative breast cancer (TBNC) has also been shown to be significantly correlated with tumor proliferation and metastasis 12-14." (PMID 40861810, 2025). "We showed that upregulation of SGO1 expression was related to adverse clinical outcomes in patients with lung cancer." (PMID 35592680, 2022). "Results confirmed that SGO1 was significantly upregulated in lung cancer tissues and cell lines, especially in A549 cells." (PMID 35592680, 2022). "To investigate the molecular causes that led to high incidence of lung carcinomas in RAG1−/− Sgo1−/+ mice, we performed RNAseq-transcriptome analyses using normal-looking lung tissues from RAG1−/− (N=3) and RAG1−/− Sgo1−/+ (N=3) mice." (PMID 27526110, 2016). "Sgo1 is essential for sister chromatid cohesion during mitosis and its depletion has been shown to induce cell death in cervical carcinoma and lung cancer cells." (PMID 25638162, 2015). "The GEO dataset was also utilized to validate the diagnosis of SGO1 in lung cancer." (PMID 35592680, 2022). "Furthermore, we showed that the SGO1 protein expression in LUAD was significantly increased in lung cancer tissues." (PMID 35592680, 2022). "While splicing variants of Sgo1 have been implicated centrosome instability and chromosome instability in colon and lung cancers, the role of the full-length Sgo1 in cancers has not been investigated." (PMID 25638162, 2015). "As lung carcinomas preferentially developed on the RAG1−/− background, we hypothesized that adoptive immunity is involved in suppressing CIN cells in the lung, and that genes or proteins involved in the immune system would be misregulated in Sgo1." (PMID 27526110, 2016).
colon cancer (5 papers, 2013 to 2023). "In human colon cancers, Sgo1 mRNA level is decreased, and siRNA-mediated inhibition of Sgo1 in the colon cancer cell line HCT116 resulted in genomic instability." (PMID 23734346, 2013). "In colon cancer, a tumor-derived P1 variant was identified as a negative regulator of the full-length Sgo1 in the cell." (PMID 25638162, 2015). "Chromosome cohesion, a main process that Sgo1 influences, is frequently defective in colon cancer." (PMID 23734346, 2013).
prostate carcinoma (4 papers, 2019 to 2025). A carcinoma that arises from epithelial cells of the prostate gland. "It has been shown that SGO1 was highly expressed in prostate cancer and associated with adverse prognosis and immune infiltration." (PMID 35592680, 2022). "Previous studies reported that SGO1 promotes the proliferation and metastasis of prostate cancer via activating the AKT-mediated signaling pathway." (PMID 35592680, 2022). "SGO1 was increased in human prostate cancer and correlated with the patients’ TNM stage, lymph node metastasis, distant metastasis, and poorer survival." (PMID 35592680, 2022). "It has been suggested that SGO1 was highly expressed in human prostate cancer tissues and cell lines." (PMID 35592680, 2022).
breast tumors (3 papers, 2014 to 2023). "Also, E2F1, E2F2, E2F3, Mps1/TTK, BubR1, NDC80 (HEC1), Nek2, and Sgo1 significantly co-overexpress in breast tumors." (PMID 29100415, 2017).
glioma (3 papers, 2016 to 2025). A benign or malignant brain and spinal cord tumor that arises from glial cells (astrocytes, oligodendrocytes, ependymal cells). "Especially, the expression of SGO1 was positively linked with the majority of immune inhibitors, and immunostimulators in THCA, KIPAN (pan-kidney cohort), KIRC, and GBMLGG (glioma)." (PMID 40861810, 2025). "Expression of MYCN correlated with that of SGO1/SGO2, except in lower-grade gliomas, and SGO1/SGO2 expression tended to be higher in some MYC-overexpressing cancers." (PMID 27539729, 2016).
lung adenocarcinoma (3 papers, 2016 to 2022). A carcinoma that arises from the lung and is characterized by the presence of malignant glandular epithelial cells. "In this study, adoptive (T/B-cell based) immunity-deficient RAG1−/− Sgo1−/+ double mutant mice developed lung adenocarcinomas more aggressively than did Sgo1−/+ or RAG1−/− mice, suggesting immune system involvement in CIN-mediated lung carcinogenesis." (PMID 27526110, 2016). "However, the underlying biological function and potential mechanisms of SGO1 driving the progression of lung adenocarcinoma remain unclear." (PMID 35592680, 2022). "Finally, we determine that SGO1 regulated the cell proliferation and cell apoptosis of lung adenocarcinoma in vitro." (PMID 35592680, 2022). "In conclusion, our data suggested that SGO1 could be a novel prognostic biomarker for lung adenocarcinoma." (PMID 35592680, 2022).
cervical carcinoma (2 papers, 2013 to 2015). A carcinoma arising from either the exocervical squamous epithelium or the endocervical glandular epithelium. "In addition, ectopic expression of some key meiotic genes was also reported in primary tumours, for example MOS in NSCLC, DMC1 in cervical cancer, SPO11, REC8, SGO1 and HORMAD1 in melanoma." (PMID 24025698, 2013).